RNU6-237P (RNA, U6 small nuclear 237, pseudogene)
Gene: Small nuclear RNA gene on chromosome 16 (74,456,541 to 74,456,611, forward strand). Ensembl gene ENSG00000251794.
Homologues: Orthologues: chimpanzee U6 (90% identical), mouse Gm25578 (83% identical), rat LOC120099418 (70% identical). Paralogues in human: RNU6-144P (85% identical), RNU6-164P (83% identical), RNU6-20P (83% identical), RNU6-25P (83% identical), RNU6-29P (83% identical), RNU6-39P (83% identical), RNU6-854P (83% identical), RNU6-1 (82% identical), RNU6-1029P (82% identical), RNU6-1124P (82% identical), RNU6-1189P (82% identical), RNU6-128P (82% identical), and 1283 more.